CDKN2A (cyclin dependent kinase inhibitor 2A)
Diseases named in the same sentence as CDKN2A in open-access papers (continued):
Sharing a sentence is not in itself a finding about the gene and the disease.
tumor (continued). "Specifically, a clinical study highlighted that reduced somatic copy number of the CDKN2A gene was linked to larger tumors, higher tumor stage, presence of tumor necrosis and microvascular invasion, and could independently predict prognosis." (PMID 40177240, 2025). "This may be due to tumor-specific effects or to the fact that at least some cancer-promoting roles previously attributed to CDKN2A LoF are in fact triggered by the loss of other 9p21 genes." (PMID 39753721, 2025). "Similarly, CDKN2A can lose its tumor-suppressive functions, also caused by mutations and other mechanisms." (PMID 41155171, 2025). "Specifically, we observed gains or amplifications of Myc, Pdgfra, and Cdkn2a, or loss of Pten, all of which influence cell pathways involved in cell cycle regulation, metabolic rewiring, or stress response, and are heterogeneously present in tumor cells." (PMID 40520013, 2025). "In the context of CDKN2A-associated therapeutic approaches, CDKN2A expression is linked to immune cell infiltration and immune regulation pathways, which could influence the tumor microenvironment and response to immunotherapy." (PMID 39925808, 2025). "We also report a comparable frequency of loss of the CDKN2A gene (25% in our tumour group) to those described by Bui and colleagues by analysing the Foundation One Medicine database (n = 372, 21% of cases) and to that reported in the TCGA Adult Soft Tissue Sarcoma study (n = 44, 20.5% of cases)." (PMID 40415599, 2025). "Increased tumor aggressiveness in NHL is linked to loss of CDKN2A function." (PMID 40321894, 2025). "The copy number profile observed in ccfDNA mirrored that of the tumor, showing large chromosomal gains (1q, 7p, 8q, 9q, and 17q) and losses (6p and 9p), as well as focal deletions in the CDKN2A, SUZ12, and SMARCA2 genes associated with the transition from PN to ANNUBP." (PMID 41463204, 2025). "However, mutations or inactivation of CDKN2A can diminish its ability to suppress tumor cells, leading to rapid proliferation and differentiation." (PMID 39925808, 2025). "In addition, a retrospective, single-center study of resected brain metastases across tumor types identified high rates of CDKN2A mutation and CDKN2A/B co-deletion in brain metastases from multiple tumor types." (PMID 40457397, 2025). "The residual tumor cells/clones may evolve by gaining distinct mutations (e.g., CDKN2A) or migrate to different tissues/TMEs, leading to tumor growth and disease relapse." (PMID 40876452, 2025). "In examining changes in p16—a tumor suppressor and known PD biomarker of DNMT inhibitors—we measured treatment-induced increases in the number of promoter hypomethylation sites for the p16-encoding gene CDKN2A in tumor specimens from 7 of the 8 assessed patients." (PMID 41428220, 2025). "Tumor grade, CDKN2A/B loss, and/or ≥1 focal amplification were associated with reduced survival." (PMID 39584448, 2025).
tumor (continued). "The associated low levels of aging markers may be linked to the inhibition of the CDKN2A gene; however, the observation of P16 positivity in tumor cells indicates its potential to promote tumorigenesis." (PMID 39325939, 2024). "We hypothesize that CDKN2A ALT leads to enrichment of tumor mutation-specific neoantigens on the cell surface, which is beneficial to the recognition and attack of immune cells." (PMID 38822443, 2024). "Furthermore, both univariate and multivariate Cox regression analyses demonstrated that age, tumor stage, and CDKN2A expression were independent prognostic risk factors for patients with SCLC (p < 0.05)." (PMID 38206516, 2024). "Additionally, we explored the abnormal signal transduction pathways associated with CDKN2A imbalance and mapped the microenvironment niche of tumor regions with CDKN2A expression." (PMID 38888512, 2024). "CDKN2A has important correlations with tumor-associated macrophages and immune infiltrates." (PMID 39272711, 2024). "In a mouse model, CDKN2A loss accelerated KRASG12D-driven tumor growth." (PMID 38310130, 2024). "CDKN2A/B loss was significantly reduced in lymph nodes compared to primary tumor (p = 0.006)." (PMID 38733174, 2024). "Therefore, COAD was the only comprehensively analyzed tumor to show a diagnostic and prognostic potential characteristic during high upregulation of CDKN2A." (PMID 38894777, 2024). "Therefore, we used GEPIA, UALCAN, and Kaplan-Meier plotter particularly across adenocarcinoma to investigate CDKN2A prognosis by studying its high expression association with the patient’s overall survival rate to show the tumor progression." (PMID 38894777, 2024). "CDKN2A has been shown to be a tumor suppressor in pNETs, and focal CDKN2A loss has been observed." (PMID 39062773, 2024). "CDKN2A MU were associated with poor prognosis in as many as six primary tumor types." (PMID 38822443, 2024). "Additional driver mutations have been found to involve the neurofibromin 1 (NF1) and the KIT (1–2%) genes, while mutations associated with tumor development have been observed in the cyclin-dependent kinase inhibitor 2A (CDKN2A) gene, a well-known cell cycle regulator." (PMID 39199632, 2024). "In addition, for those individuals with advanced kidney renal clear cell carcinoma (KIRC), CDKN2A deletion is significantly associated with worse overall survival (OS) in patients with tumor-infiltrating T cells after PD-1 blockade." (PMID 38822443, 2024). "Overall, cooccurring deficiencies in BAP1, NF2, and CDKN2A/B might play an instructive role in tumor immunity and are closely related to patient prognosis." (PMID 38879686, 2024). "One tumor was found to have a TERT promoter mutation as well as a homozygous deletion of CDKN2A/B." (PMID 38720399, 2024). "Furthermore, the authors successfully established a cell line containing the BRAFV600E mutation, TERT promoter mutation and CDKN2A/2B loss from recurrent tumour derived from an autopsy." (PMID 39107839, 2024). "Hypermethylation of CDKN2A promoter is a leading cause of reduced CDKN2A expression in tumor cells." (PMID 38918694, 2024). "Indeed, loss of CDKN2A in one EHE GEMM was found to cooperate with the WWTR1::CAMTA1 fusion to enhance tumor progression." (PMID 39283723, 2024). "This means that cooccurring mutations in NF2 with CDKN2A/B may have synergistic effects on tumor incidence and malignancy." (PMID 38879686, 2024).
tumor (continued). "However, their analysis revealed that the patients who developed a tumor at < 30 years old accounted for < 20% of the total CDKN2A variant carriers (19.1%, 4/21)." (PMID 38961426, 2024). "Indeed, our further exploration of public Bueno and TCGA datasets demonstrated that especially high CDKN2A transcript levels occurred in a subset (12%) of CDKN2A expressing tumours that were associated with poorer survival." (PMID 36453028, 2024). "CDKN2A mutations were found in 2 patients’ (1 and 10) tumor tissue." (PMID 38103030, 2024). "Three LGG patients were IDH—wildtype; one patient carried TRIM33–NTRK2 fusion; two other patients had genotypes more specific for HGG tumor types (CDKN2A deletion, PTEN mutation, and PTEN deletion in one case and TERTp mutation, PTEN mutation, and NF1 mutation in another)." (PMID 39684714, 2024). "This could be because the loss of CDKN2A function inhibits cell cycle progression, promoting tumor growth." (PMID 39273409, 2024). "Moreover, earlier investigations have demonstrated that CDKN2A DEL is associated with the establishment of a cool tumor immunological microenvironment." (PMID 38822443, 2024). "The CDKN2A gene encodes two proteins: p16INK4a and p14ARF, both of which are tumor suppressors." (PMID 39581873, 2024). "From this model it will, however, remain unclear if the mutations in BAP1 and CDKN2A were conserved from the originating tumor or acquired during passaging in the commercial cell lines." (PMID 37345150, 2023). "Interestingly, the combination of BRAF V600E and CDKN2A loss likely leads to tumor transformation and higher tumor grade." (PMID 38318325, 2023). "Interestingly, both of them showed a direct and consistent physical interaction with CDKN2A, a tumour suppressor whose deletion is widely associated with GBM tumourigenesis." (PMID 36769158, 2023). "CDKN2A, a gene frequently associated with tumor progression, was homo-deleted in both samples." (PMID 37072390, 2023). "Therefore, loss of function of CDKN2A should lead to unchecked cell-cycle progression and tumor progression." (PMID 37093270, 2023). "Notably, chromosomal gain in chromosomes 4–9, 17 and 18 and loss in the short arm of chromosome 9 associated with homozygous 9p21.3 deletion involving CDKN2A/B locus were identified in both patient tumor and PDX sample." (PMID 37280243, 2023). "When the gene encoding this protein, CDKN2A, undergoes mutations and/or deletions, the antitumor action is ineffective or non-functional, thus accelerating the cell cycle and being correlated with tumor proliferation." (PMID 37623944, 2023). "CDKN2A is a tumor suppressor gene encoding the p16 protein, a key regulator of the cell cycle." (PMID 36900302, 2023). "The p16 protein (also known as p16INK4a), encoded by the cyclin-dependent kinase inhibitor 2A (CDKN2A) gene, is a tumor suppressor, inhibiting cyclin-dependent kinases (CDK4/6) that maintain Rb in a phosphorylated state when bound to cyclin D1 (encoded by CCND1)." (PMID 37109525, 2023). "In addition, tumor volume is also predictive, with tumors greater than 8 cm being less likely to harbor an underlying CDKN2A copy loss." (PMID 38135704, 2023). "Tumour genomic data were typical for a rHGG/rGBM population, including the presence of mutations in the CDKN2A/B (encoding p16) tumour suppressor pathway, previously shown to complement viral replication of oHSVs, such as CAN-3110, with defects in the viral ribonucleotide reductase function." (PMID 37853118, 2023). "However, we observed a significant association between CDKN2A expression and tumor stage, as well as nerve invasion status." (PMID 37950153, 2023).
tumor (continued). "Recent studies demonstrated that response to BRAF+MEKi in patients with germline CDKN2A PVs was not inferior to data from clinical trials and real-world studies, while the response rate to immunotherapy was superior in CDKN2A PVs carriers, likely due to an increased tumor mutational load." (PMID 36901733, 2023). "High-grade NMIBC tumours can be characterised by homozygous deletion of CDKN2A (encodes p16INK4a)." (PMID 36928373, 2023). "CDKN2A encodes p14ARF and INK4a and plays a role in regulating tumor suppression." (PMID 37667984, 2023). "One of the most critical CNAs that drive tumor progression is CDKN2A/B loss." (PMID 38012788, 2023). "In multivariate Cox proportional hazard analyses including patient, tumor, and treatment factors, CDKN2A/B co-deletion in the brain metastasis was associated with increased risk of local (HR 4.07, 95% CI 1.32-12.54, P = 0.014) and remote (HR 2.28, 95% CI 1.11-4.69, P = 0.025) CNS progression." (PMID 36915611, 2023). "Having identified the differential expression of Arf in both models, we investigated whether modification of the Cdkn2a gene, encoding p19ARF, is involved in tumor formation in the GMYC model." (PMID 36869047, 2023). "CDKN2A, as a tumor suppressor gene, encodes the protein of p16, which could arrest cell cycle of cells." (PMID 35042525, 2022). "By mapping both KRAS and CDKN2A mutations, we identified several cells in the ADM_tumor population with either a KRAS mutation (n = 1) or CDKN2A mutation (n = 7), although this was not as widespread as the predicted PanIN populations (KRAS: 23 cells; CDKN2A: 163 cells)." (PMID 35995947, 2022). "The closest protein-coding gene to this SNP is CDKN2B (cyclin dependent kinase inhibitor 2B) which is adjacent to the tumor suppressor gene CDKN2A (Cyclin-Dependent Kinase 4 Inhibitor A) in a region that is frequently mutated and deleted in a wide variety of tumors." (PMID 35884374, 2022). "This suggests that appropriate combinations with CDK4/6 inhibitors in PDAC may enhance immune response in tumors with loss of CDKN2A through tumor-centric and possibly TME mechanisms." (PMID 35273962, 2022). "In addition to the inactivation of Cdkn2a/2b, Met amplification was significantly associated with increased tumor size in Fe-NTA-induced RCC." (PMID 35326646, 2022). "CDKN2A is a tumor suppressor gene that encodes the p16INK4A protein." (PMID 36086716, 2022). "After intersecting tumour-associated DEGs with cuproptosis-related genes, CDKN2A was identified as a key gene, which may play a critical role in tumour development through cuproptosis." (PMID 36699463, 2022). "However, a variety of other mutations exist, especially in tumor suppressor genes, such as CDKN2A, SMAD4, ARID1 or BRCA2." (PMID 36078040, 2022). "It has been previously shown that long-term OE of the inflammation-related pathway Ink4/Arf locus, comprising Cdkn2a-Cdkn2b genes that encode four potent tumor suppressors, namely p16Ink4a, p19Arfand, p15Ink4b, and p21Cdkn1a, inhibited the efficiency of in vitro reprogramming." (PMID 35947961, 2022). "Cdkn2a encodes a cell-cycle inhibitor and is a well-known tumor suppressor." (PMID 35565312, 2022). "Cyclin-dependent kinase inhibitor 2A (CDKN2A; 9p21.3) encodes p16INK4A and p14ARF, which are vital regulators of the cell cycle and play a significant role in programmed cell death through their tumor-suppressive activities." (PMID 35932035, 2022). "These patients may be attributed to the tumor heterogeneity and the aberrant expression of driver genes, such as CDKN2A mutation or EGFR amplification." (PMID 35267417, 2022). "CDKN2A loss correlates with reduced immune infiltrates in several tumor types, including PDAC." (PMID 35273962, 2022).
tumor (continued). "Whether the linkage between IFNs and Cdkn2a/b is biologically meaningful remains to be determined, but it is noteworthy that both type I IFNs and Cdkn2a-encoded proteins limit viral infection, which may have been co-opted for tumor suppression." (PMID 36344707, 2022). "Asbestos-exposed mice with heterozygous deletions of Cdkn2a, Nf2, and Bap1 have each been shown to have an increased risk of MMe development compared to wildtype mice, supporting the importance of these tumor suppressor genes as drivers in MMe pathogenesis." (PMID 35804881, 2022). "Notably, we observed HLA LOH and CDKN2A/B loss co-occur in 9 patients (Fisher exact test P = 0.003) and most tumor regions (Fisher exact P = 5 × 10−7)." (PMID 36536472, 2022). "Multiomic analysis revealed that CDKN2A may be associated with cell cycle and immune cell infiltration in the tumour microenvironment and is important for maintaining systemic homeostasis in the body." (PMID 36699463, 2022). "CDKN2A and CDKN2B encode three well-established tumor suppressors: p15, p16, and p14ARF." (PMID 35626065, 2022). "CDKN2A is a canonical tumor suppressor that regulates cell cycle, the loss of which may lead to perturbed chromosomal stability and poor prognosis." (PMID 36081566, 2022). "Intriguingly, both protein isoforms encoded by CDKN2A, ARF (p14) and INK4A (p16), function as tumor suppressors by regulating cell proliferation, linking CDKN2A protein function to the cellular phenotype observed to be regulated by both linear and circular ANRIL21." (PMID 35546161, 2022). "To test whether the gene expression of one of the several transcription variants of CDKN2A, p14ARF reflects ccRCC-associated changes, we determined and compared the normalised mRNA levels of each normal and tumour sample." (PMID 35586183, 2022). "CDKN2A mutation was identified in 9–22% of all HNSCC tumours." (PMID 34829777, 2021). "In addition, we also explored the association between CDKN2A expression level and tumor mutation burden (TMB) and microsatellite instability (MSI)." (PMID 35004697, 2021). "CDKN2A (9p21.3) encodes P16 protein that is a tumor suppressor." (PMID 34796198, 2021). "Amplification of TERT and loss of CDKN2A/CDKN2B detected in the tumor by next gene sequencing suggests that they may play an important role in this case." (PMID 34127009, 2021). "An earlier study by Oshima suggested that mutations in SMAD4 were significantly associated with tumor size, lymphatic infiltration, and lymph node metastasis, whereas CDKN2A mutations were associated with lymphatic infiltration and extensive postoperative metastasis." (PMID 35127473, 2021).